BRAF (B-Raf proto-oncogene, serine/threonine kinase)
Diseases named in the same sentence as BRAF in open-access papers (continued):
Sharing a sentence is not in itself a finding about the gene and the disease.
melanoma (continued). "In order to validate this finding, we performed the Bisbee splicing analysis on an independent melanoma cohort, consisting of 37 patients with BRAF wild-type recurrent tumors including 13 cutaneous, 7 mucosal, 10 uveal, 5 acral, 1 melanoma of unknown primary." (PMID 34031440, 2021). "More examples of predictive molecular biomarkers routinely tested in clinical settings include the following: KIT/PDGFRA in gastrointestinal stromal tumors, BRAF/NRAS/KIT in advanced melanoma, IDH1/1p/19q codeletion/MGMT promoter methylation in brain neoplasms." (PMID 33670699, 2021). "Taken together our results emphasize SOX4 as a potential therapeutic target in BRAF driven melanoma which could be attacked by pharmaceutically, e.g., by miR-129-5p mimics." (PMID 34063443, 2021). "The LIDC criteria as scored by a thorax radiologist also failed to discriminate the BRAF mutation status in melanoma lung metastases." (PMID 33915880, 2021). "Importantly, melanoma cells showing resistance to BRAF inhibitors were also sensitive to SAMMSON silencing." (PMID 34526609, 2021). "Accordingly, we observed that Ptch1 is endogenously expressed in various melanoma cell lines carrying or not a BRAF mutation." (PMID 33810240, 2021). "W9 mAb increased the sensitivity of human BRAFV600E melanoma cells to BRAF inhibitors." (PMID 33898309, 2021). "We examined whether CTCs have potential as biomarkers by checking the number of CTCs, as well as the BRAF genotype of individual CTCs, in melanoma patients undergoing BRAF/MEK inhibitor treatment." (PMID 33731038, 2021). "Eighteen (40%) patients had a BRAF-mutated and 8 (18%) had an NRAS-mutated melanoma." (PMID 34073477, 2021). "Among individuals with darker phenotypes, the MC1R variants are associated with BRAF V600E-mutant melanomas on non-sun-exposed skin." (PMID 34442055, 2021). "Also, ligand-independent EPHA2 signaling triggered the adoption of a therapy-induced, BRAF inhibitor resistant-metastatic melanoma phenotype through PI3K-AKT signaling." (PMID 33572284, 2021). "The observed profile separation between the different BRAF mutant melanoma xenografts supports the hypothesis of metabolic heterogeneity irrespective of the genetic driver mutation." (PMID 33498757, 2021). "Thanks to the improved understanding of the features and drivers of melanoma, therapeutic agents targeting the mitogen-activated protein kinase pathway (e.g., BRAF inhibitors, MEK inhibitors) have been approved for patients with BRAF-mutated melanoma." (PMID 33621202, 2021). "In phase 3 trials in advanced BRAFV600E/K mutant melanoma, the incidence of rash is substantially lower with the combination of the BRAF-inhibitor dabrafenib and the MEK-inhibitor trametinib (all-grade 28%) as compared to trametinib monotherapy (all-grade 57%), at the same trametinib dosing." (PMID 33921947, 2021). "According to the whole-exome sequence analysis of melanoma patients carried out by The Cancer Genome Atlas (TCGA), the following four main melanoma mutants can be identified: BRAF, Neuroblastoma Rat Sarcoma (NRAS), Neurofibromatosis type 1 (NF1) and Triple-wild-type." (PMID 34683910, 2021). "It is noteworthy that the implementation of BRAF and MEK inhibitors in clinical practice is a testimony of the impressive improvement in outcomes by targeting a subset of oncogenic driver mutations in melanomas." (PMID 34831002, 2021). "Furthermore, RNA and DNA sequencing of 80 Spitz tumors (ST), 26 Spitz melanomas (SM) and 22 melanomas with spitzoid features (MFS) showed that in STs and SMs, kinase fusions were prevalent, while in MSFs, mostly BRAF, NRAS and NF1 mutations were present." (PMID 33669371, 2021). "A recent study also demonstrated that the downregulation of E2F1 in melanoma cells could induce cell senescence and cell death and further increase the sensitivity of melanoma cells to BRAF inhibitors." (PMID 34564711, 2021).
melanoma (continued). "Notably, we observe a significant induction of CD40+SOX10+ melanoma cells in the tumors of melanoma patients post BRAF inhibitor treatment by multiplex IHC analysis." (PMID 34092233, 2021). "In addition, chronic exposure of cultured melanoma cells to BRAF and/or MEK inhibitors and melanocytic antigen-specific T cells promotes the invasive switch, a phenotype that can be recapitulated in vivo." (PMID 34604096, 2021). "Indeed, the dabrafenib plus trametinib combination in BRAF mutant melanoma patients has a 34% 5-year overall survival rate." (PMID 34830962, 2021). "Discontinuation of BRAF inhibitor treatment in resistant melanoma cells results in hyperactivated MAPK signaling, which may be detrimental to these cells." (PMID 32767816, 2021). "This was not evident in the current study and it can be considered additional evidence that a CT-based radiomics signature probably does not exist for the BRAF mutation status in melanoma lung metastases." (PMID 33915880, 2021). "We hypothesize that once melanoma cells have acquired resistance to treatment with BRAF and MEK inhibitors by upregulation of MAPK activity they will become more sensitive to DUSP4 inhibition." (PMID 32767816, 2021). "Systemic therapy for melanoma with combined BRAF–MEK inhibitors was started." (PMID 34746007, 2021). "The role of AKT1 in enhancing the capacity of both glycolytic and oxidative metabolism, thereby maintaining bioenergetic levels after treatments such as BRAF inhibition, makes it an important factor to study and potentially target to limit the plasticity of melanoma cells." (PMID 34831420, 2021). "It is worth mentioning that BRAF status testing is imperative to the treatment choice; in general, immunotherapy is offered to both patients with BRAF-positive and BRAF-negative melanoma, whereas targeted therapy (BRAFi and MEKi) is only used for patients who test positive for the BRAF mutation." (PMID 34914610, 2021). "RhoA may also act through downstream effectors like YAP1, which has already been shown to confer resistance to BRAF/MEK inhibitor treatment in melanoma." (PMID 33807778, 2021). "However, in practice, patients harboring LM from melanoma have typically already been treated with BRAF and MEK inhibitors." (PMID 34859236, 2021). "It is possible, that the patients with BRAF mutant melanoma, treated with targeted therapy had worse outcomes because there was no access to PD-1 inhibitors or combination immunotherapy after progression, however, pembrolizumab was available within nine months of dabrafenib and trametinib access." (PMID 34677256, 2021). "For patients with BRAF wild-type and BRAF V600-mutant melanoma, the objective response rate was 39.8% (447/1124) and 34.3% (149/434), 4-year progression-free survival rate was 22.9% (257/1124) and 19.8% (86/434), and 4-year overall survival was 37.5% (421/1124) and 35.1% (152/434), respectively." (PMID 34804979, 2021). "In addition, TGF-β signaling was reported to mediate the up-regulation of microRNA-125a (miR-125a) expression and suppression of pro-apoptotic pathway, which accounted for the acquisition of BRAFi resistance in BRAF-mutant melanoma patients." (PMID 34917620, 2021). "However, this difference appeared to be driven by the subgroups of postmenopausal women and female patients with a BRAF V600 mutant melanoma." (PMID 34572865, 2021). "Moreover, upregulation of VEGFR-1 was evidenced as a mechanism of resistance to the mutant-BRAF inhibitor vemurafenib in human melanoma cells." (PMID 33918490, 2021). "This is further supported by a recent phase 3 COMBI-I clinical trial (NCT02967692) that examined the efficacy of a novel PD-1 inhibitor (spartalizumab) in combination with dabrafenib and trametinib in patients with unresectable and/or metastatic BRAF V600E mutant melanomas." (PMID 33807608, 2021).
melanoma (continued). "Moreover, several plasma metabolites were uniquely regulated in either A375 or WM47 melanoma samples, whereas only a few metabolites were consistently up- or downregulated in plasma samples from both BRAF mutant melanomas compared to NTM." (PMID 33498757, 2021). "Since the level of bilirubin was negatively correlated with the clinical outcome of patients who were treated with vemurafenib, we wondered whether bilirubin could abrogate the anti-cancer effects of vemurafenib in BRAF mutant melanoma models." (PMID 34222023, 2021). "For instance, BRAF mutations seem to enhance carcinogenesis resulting from UVB, meaning fewer exposures might be required for melanocyte progression into melanoma." (PMID 34680367, 2021). "Thus in melanoma cells, apoptosis induction by different agents as an iron-substituted nucleoside analog, indirubin derivatives as well as by protein kinase B or BRAF inhibition was shown to be largely ROS-dependent." (PMID 33807213, 2021). "Consequently, these findings indicate the controversy of the theory that BRAF oncogene activation is an early crucial event in melanoma progression." (PMID 33391380, 2021). "On the other hand, the same study showed that the dermoscopic presence of dotted vessels was a negative predictor of BRAF-mutated melanomas." (PMID 33954019, 2021). "There is some pre-clinical evidence that in BRAF-wildtype melanoma, the combination of MEK inhibitors with ICIs may enhance anti-tumor effects." (PMID 33804800, 2021). "Thus far, the miR-204, miR-211, as well as miR-410-3p, were shown to be induced by BRAF or MEK inhibitor and to contribute to resistance to BRAF inhibitor in melanoma by enhancing the activity of downstream pathways, such as MEK or ERK." (PMID 34063443, 2021). "We treated the melanoma cell lines A375 and M14 with the BRAF kinase inhibitor vemurafenib." (PMID 33766731, 2021). "Moreover, a reduction in ctDNA occurring during treatment is considered an independent predictor of response to BRAF inhibitor in melanoma." (PMID 35008245, 2021). "Consequently, drugs targeting FGF/FGFR signaling are considered in combination treatment for melanoma patients showing resistance to (BRAF)/MEK inhibitors (ongoing LOGIC-2 phase II clinical trial)." (PMID 33918490, 2021). "The effect was selective for melanoma cells, including BRAF inhibitor-resistant cells." (PMID 34725562, 2021). "Despite the advances in the treatment of malignant melanoma with BRAF/MEK targeted agents and immunotherapy, a poor prognosis for advanced disease is noted and therefore cyclin-dependent kinase inhibition either as single agent or in combination with established treatment are under clinical trials." (PMID 33917849, 2021). "The toxicity spectrum between Chinese and Caucasian patients with melanoma who were treated with BRAF inhibitors (BRAFi) may differ." (PMID 33868987, 2021). "Retrospective experience is available for combination BRAF inhibitors and CNS directed radiotherapy for melanoma patients with brain metastases and may inform the use of such combinations in pediatric CNS tumors." (PMID 34277419, 2021). "Additionally, the combination of CDK4 and MAPK pathway inhibitors has shown tumor regression in xenograft models of cancers with KRAS, NRAS, or BRAF mutations, particularly BRAF- and NRAS-mutant melanoma, with promising results from phase I clinical studies." (PMID 34309585, 2021). "Finally, BRAFV600E melanoma cells treated with BRAF or MEK inhibitors significantly decreased RMEL3 expression levels, suggesting RMEL3 as a downstream effector of ERK signaling and as a promising candidate for pharmacological target." (PMID 33503876, 2021). "Looking beyond targeting Ras directly, BRaf inhibitors developed to target the popular V600E mutant (vemurafenib, dabrafenib, etc.)have been pursued for their disruption of the MAPK-ERK pathway in cancers with BRaf-driven cancers, including BRaf mutant melanoma and NSCLC." (PMID 34680208, 2021).
melanoma (continued). "BRAF inhibitors are an approved therapy for BRAFV600E melanoma." (PMID 33564819, 2021). "Finally, the combination of ECCA with a BRAF inhibitor significantly enhanced the growth inhibition of melanoma cells." (PMID 34103468, 2021). "In particular, there is a higher frequency of BRAF mutations in melanomas of younger patients, melanomas located on the trunk, lesions of the superficial spreading histological subtype, and melanomas that develop on skin without chronic actinic damage." (PMID 33954019, 2021). "Since both the MAPK/ERK and PI3K/AKT signaling pathways converge into mTORC1, this signaling pathway may be crucial for the efficacy of targeted therapy in patients with BRAF-mutant melanoma." (PMID 34304249, 2021). "In the current study, none of the radiomics features had any discriminative value; therefore, it can be concluded that radiomics features of melanoma lung metastases are not related to the BRAF mutation status." (PMID 33915880, 2021). "Similar to in melanoma, colon, and thyroid cancer, BRAF V600E marks poor outcomes." (PMID 34944576, 2021). "Recently, BRAF V600E was found to influence the composition of the tumor microenvironment, modulating both immune cell infiltration and soluble mediators in thyroid and melanoma cancer." (PMID 34707096, 2021). "However, similarly to MEK and RAF inhibitors, targeting ERK as a monotherapy failed to achieve clinical responses in patients with RAS mutations, although some responses were observed in patients with BRAF-mutant melanoma." (PMID 34200676, 2021). "Although the contribution of mutant NRAS and BRAF to MM progression appears to be less common than melanoma of the skin, more components in the MAPK pathway of MM tend to undergo mutations or copy number changes, rendering inhibition of MAPK signaling transduction more challenging." (PMID 34350118, 2021). "Hence, it was recommended by the National Institute for Health and Care Excellence for BRAF-positive advanced melanomas." (PMID 34914610, 2021). "NRAS mutations usually occur independently of BRAF mutations, but 10–20% of melanomas have point mutations in NRAS codons 12, 13 or 61 that may be mutually exclusive with BRAF mutations." (PMID 34441278, 2021). "To date, patients with BRAF-mutant melanoma can be treated with TTs and ICIs." (PMID 33801689, 2021). "Moreover, the addition of cyclin dependent kinase 4/6 inhibitors (CDK4/6i) have been shown to greatly extend duration of response in combination with BRAF-MEK inhibitors (BRAF-MEKi) in pre-clinical models of melanoma." (PMID 34944961, 2021). "In melanoma, intra-tumor heterogeneity has been described for the presence or absence of BRAF mutations, but more detailed analyses on mutational patterns were still lacking at that time." (PMID 33535416, 2021). "Furthermore, Melanoma was screened for CRISPRa library and positively selected by the BRAF protein kinase inhibitor vemurafenib (PLX)." (PMID 34598686, 2021). "MEK inhibition has revealed surprising anti-tumor effect in BRAF-mutant melanoma." (PMID 34001246, 2021). "RAC1P29S is the third most commonly mutated codon in human cutaneous melanoma, after BRAF V600 and NRAS Q61, and one of the most prominent driver mutations in RAC1 with a frequency of approximately 5% and up to 10% in chronically sun-exposed melanomas." (PMID 34827551, 2021). "The experience to date with HER2-targeting agents has revealed a degree of complexity with this amplified oncogene that sets it apart from oncogenes activated through gene mutation or fusion events such as EGFR or Alk in lung cancers, Bcr-abl in leukemias, or BRAF in melanomas." (PMID 33907275, 2021). "The OS was 9.53 and 15.64 months, and the ORR was 5.0 and 18.3% in patients with and without BRAF-mutated melanoma, respectively, although the difference was not statistically significant." (PMID 34115870, 2021).
melanoma (continued). "PLX8394 was also shown to reduce ERK1/2 reporter activity and induce apoptosis ex vivo in BRAF-mutant melanoma xenografts with greater efficacy than vemurafenib; however, studies in vivo demonstrated acquired resistance through ERK1/2 reactivation but with different ERK-inhibitor sensitivity." (PMID 33807778, 2021). "Consequently, there are great unmet needs for developing novel agents capable of overriding drug resistant melanoma harboring pan-BRAF mutants." (PMID 33917428, 2021). "We found increased expression of miR-129-5p during BRAFi treatment of BRAF- mutant melanoma cells." (PMID 34063443, 2021). "Interestingly, Ocoxin cotreatment with Vemurafenib partially overcame TS-fibroblast-mediated resistance in melanoma cells, boosting the anticancer activity of BRAF inhibition." (PMID 33669949, 2021). "By contrast, the genetic profiles of Spitz melanoma (mutations in HRAS and kinase fusions in ROS1, NTRK1, NTRK3, ALK, BRAF, MET, and RET) as well as of melanoma arising in blue nevus (mutations in the Gαq signalling pathway) are not encompassed within the TCGA classification." (PMID 34277420, 2021). "Furthermore, the level of circulating MMP-9 has been cited as a good candidate to evaluate the response to BRAF inhibitors in melanoma patients." (PMID 34604096, 2021). "BRAF is commonly seen in the MAPK pathway (RAS/RAF/MEK/ERK pathway), and mutation of this pathway is an important factor that causes growth and development of melanoma." (PMID 34575074, 2021). "Since PK2M activity and aerobic glycolysis are upregulated in BRAF inhibitors resistant melanoma cells, treatment with benserazide results in a heightened sensitivity to suppressed PK2M expression both in vitro and in vivo, with potential therapeutic applications." (PMID 34073463, 2021). "Since vemurafenib can inhibit the growth of BRAF mutant melanoma cells via apoptosis induction, we explored whether apoptosis is involved in bilirubin-induced reversal effect of proliferation suppression triggered by vemurafenib." (PMID 34222023, 2021). "Intriguingly, in vitro inhibition of such “chromatin readers” is associated with cell cycle arrest in preclinical melanoma models, regardless of BRAF or NRAS mutational status." (PMID 34440824, 2021). "ddPCR has been shown to accurately detect alterations of intertest in non-CNS tumor blood/plasma samples including BRAF V600E alterations in melanomas and EGFR mutations in non-small cell lung cancer, both have targeted treatments available." (PMID 33925295, 2021). "One example is represented by BRAF mutation (V600E), which is a predictive biomarker of response to BRAF inhibitors in melanoma but not in colorectal cancer." (PMID 33504059, 2021). "These two mutations (BRAF and NRAS) are the most common genetic alterations in human melanoma." (PMID 33937086, 2021). "Furthermore, women treated with targeted therapy have a better ORR and PFS, leading to a better OS in women with a BRAF V600 mutant melanoma over men." (PMID 34572865, 2021). "Targeting negative regulators of MAPK signaling inhibitors such as DUSP4 and PEA15 further activates MAPK signaling and may therefore be particularly effective in eliminating melanoma cells that have acquired resistance to BRAF and MEK inhibition." (PMID 32767816, 2021). "In line with previous studies of extracranial melanomas, none of our 16 sample pairs presented coexistence of BRAF and NRAS mutations." (PMID 33578810, 2021). "In a recent review study of >85 undifferentiated and dedifferentiated melanomas, these BRAF variants were never encountered in undifferentiated melanoma and V600K was the only non-V600E variant seen." (PMID 33506327, 2021). "In this context, the histone deacetylase inhibitor vorinostat, which is well known to induce 8-oxo-G, a marker of oxidative DNA damage, was shown to dramatically increase ROS levels only in BRAF (V600E) mutant melanomas, which acquired resistance to MAPK inhibitors." (PMID 34725562, 2021).